CXCL1 (C-X-C motif chemokine ligand 1)
Diseases named in the same sentence as CXCL1 in open-access papers (continued):
Sharing a sentence is not in itself a finding about the gene and the disease.
cancer (continued). "An important factor in the development of MM is CXCL1, as the levels of this chemokine are elevated in the blood of patients with this cancer and increase with the consecutive stages of the disease." (PMID 38673949, 2024). "The correlation between increased CXCL1 expression and cancer progression, invasion, and adverse patient outcomes has led to its proposal as a non-invasive biomarker for CRC." (PMID 38979413, 2024). "Compared with siControl, siCXCL1/8 spheroids showed a significant reduction in macrophage infiltration, suggesting cancer cell CBX2-mediated regulation of CXCL1/8 expression contributes to differential macrophage infiltration." (PMID 38984891, 2024). "Chemokine (C-X-C motif) ligand 1 (CXCL1) is a chemokine that significantly affects the cell motility of various cancers." (PMID 39132161, 2024). "The role of CXCL1 in tumorigenesis in this cancer is low compared to the significance played by CXCL8/IL-8." (PMID 38673949, 2024). "MiR-485-3p bound to CXCL1 3ʹ untranslated region (3ʹUTR) to degrade CXCL1 expression, and the anti-cancer effects of miR-485-3p restoration were impaired by CXCL1 overexpression." (PMID 38536591, 2024). "Among the most recurring ligands, we found several instances that are either invariably associated to lower survival, e.g., CXCL5, CXCL1, GAL, and RPS19, or have opposite associations depending on the cancer type, e.g., CXCL9." (PMID 38723607, 2024). "In summary, CXCL1 plays a multifaceted role in cancer progression and metastasis, making it an attractive target for anticancer therapies." (PMID 39057432, 2024). "Its ability to promote metastasis is not solely dependent on the CXCR2 receptor, highlighting the multifaceted and complex nature of CXCL1 in cancer progression." (PMID 38791448, 2024). "The PMN-MDSCs-derived TNF rewire CXCL1 overproduction by cancer cells that in turns led to dysfunction and spatial exclusion of T cells from tumor core." (PMID 38817612, 2024). "TAP1 was abundantly expressed across all cell clusters, ULBP2 was primarily expressed in T cells, CXCL1 was mainly expressed in CAFs, myeloid cells, normal epithelial cells, and cancer epithelial cells." (PMID 39020010, 2024). "This means that CXCL1 is produced and secreted by the cancer cell and then increases the proliferation of the same cell." (PMID 38673949, 2024). "These include broad decreases in cytokine release, increased cancer-promoting chemokines (CXCL1 and CXCL5) and increased immunosuppressive surface proteins that likely facilitate T-cell suppression." (PMID 38542481, 2024). "These receptors are activated by multiple signaling molecules including CXCL-1, CXCL-2, CXCL-5, CXCL-8, and IL-8 released by various constituents of this environment, including cancer cells, immune cells, and cancer-associated fibroblasts." (PMID 38361931, 2024). "At the same time, CXCL1 expression in cancer cells is dependent on epidermal growth factor receptor (EGFR) ligands derived in endothelial cells." (PMID 38673949, 2024). "Bioinformatics analysis indicates that CXCL1 belongs to one of the key genes in myeloma side population cells, a MM cell population analogous to cancer stem cells in solid tumors." (PMID 38673949, 2024). "Consistent with our findings, other chemodrugs, including doxorubicin, carboplatin, oxaliplatin, and gemcitabine, have been reported to induce the secretion of CXCL1 from cancer cells and therefore to mediate the emergence of cancer chemoresistance." (PMID 39051750, 2024). "Factors such as CXCL1, CXCL2, and IL-8 released by cancer-associated mesenchymal stromal cells were also involved in the chemoresistance of ovarian cancer cells." (PMID 39394189, 2024). "The primary consequences of CXCL1 action on cancer cells include increased proliferation and enhanced migration of cancer cells." (PMID 38673949, 2024).
cancer (continued). "Apart from inducing the chemotaxis of immune cells, CXCL1 also directly promotes cancer metastasis and chemoresistance by inducing autophagy of cancer cells, activating self‐renewal of CSCs, and inducing the neoangiogenesis effects of endothelial cells." (PMID 39051750, 2024). "Subsequently, CXCL1 increases NF-κB activation in cancer cells, which leads to the mesenchymal transition of cancer cells." (PMID 38673949, 2024). "CXCL1, CXCL5, and CXCL10 have generally been considered to be pro-tumorigenic in several cancer types, as they are associated with poorer prognosis and an immunosuppressive microenvironment." (PMID 39623404, 2024). "The chemotherapeutic drugs induced cancer cells to release more CXCL1 in the TME, leading to the recruitment of MDSCs into tumors and increased S100A8/9 secretion, ultimately increasing cancer cell survival following chemotherapy." (PMID 39394189, 2024). "Among the CXCR2 ligands, especially CXCL1 and CXCL8 have often been reported to be associated with cancer progression." (PMID 38750114, 2024). "Both HO-1 and CXCL1 play complex and interconnected roles in cancer progression and represent promising targets for anticancer therapies." (PMID 39057432, 2024). "The great importance of CXCL1 in cancer processes is also shown by in vivo experiments, for example, when CXCL1 increases bladder cancer tumor growth." (PMID 38673949, 2024). "CXCR-2 ligands include CXCL-1, CXCL-2, CXCL-3, CXCL-5, IL-6, CXCL-7 and IL-8, and overall CXCLs/CXCR-2 pathway is implicated in cancer and inflammation." (PMID 38672477, 2024). "We focus on understanding how CXCL1 is involved in the cancer processes of these specific types of tumors." (PMID 38673949, 2024). "It aimed to disrupt the paracrine inflammatory loop, where chemotherapy-induced cytotoxic stress leads to TNF-α secretion by endothelial cells, promoting cancer-cell production of CXCL1/2 and recruitment of MDSCs." (PMID 39206193, 2024). "In cancer tissue, CXCL1 has been found to be upregulated by gene amplification, transcription by high basal NFkB activation, presence of proinflammatory cytokines promoting expression and other regulators of CXCL1 mRNA stability." (PMID 38393465, 2024). "Induction of CXCL1-secreting M2 TAMs through cancer cell derived visfatin (known adipokine) was reported to promote BC progression and metastasis." (PMID 39044824, 2024). "Other IFNγ-induced chemokines CCL5, CCL20, and CXCL1 were shown to be related to cancer progression and poor prognosis." (PMID 37445941, 2023). "Recent studies have reported that CXCL1 secreted by ESCC cancer cells stimulates the conversion of CAFs toward its subtype of inflammatory CAFs (iCAFs), further promoting cancer progression." (PMID 37598158, 2023). "This means that CXCL1 is involved in the reciprocal interaction of OSCC cancer cells with endothelial cells." (PMID 37408240, 2023). "CXCL1 expression occurs in cancer cells, and CXCL1 and CXCL8 expression occurs in HCC cancer stem cells." (PMID 37408240, 2023). "In one study, the conversion of normal fibroblasts to cancer-associated fibroblasts (CAFs) under co-culture conditions with OSCC lines was associated with the regulation of IL6 and CXCL1, with the latter acting in a cancer-specific manner." (PMID 37046588, 2023). "Studies revealed that chemotherapeutic drug exposure triggers ECs to secrete TNF-α and promotes CXCL1/2 expression in cancer cells, contributing to amplification of CXCL1/2-S100A8/9 loop and inducing the acquisition of therapeutic resistance." (PMID 37666809, 2023). "CXCL1 expression in cancer cells is also elevated by secretory factors such as epidermal growth factor (EGF), IL-17, protease-activated receptor 1 (PAR1), and TNF-α." (PMID 37108425, 2023). "OSCC cancer cells induce the senescence of fibroblasts; in this state, fibroblasts secrete CXCL1, which, in an autocrine manner, enhances the senescence of fibroblasts and participates in tumorigenic processes in OSCC." (PMID 37408240, 2023).
cancer (continued). "TANs can stimulate the recruitment and activation of T cells in cancer through the production of several mediators, including the chemokines CXCL1, CXCL2, CXCL10, CCL2, and CCL3, respectively." (PMID 37444436, 2023). "Following an increase in the expression of CXCL1 in cancer cells and endothelial cells as a result of VEGF, CXCL1 acts on endothelial cells, causing angiogenesis, and on cancer cells, causing their migration toward endothelial cells." (PMID 37408240, 2023). "The great importance of CXCL1 in tumorigenesis is confirmed by the correlation of CXCL1 expression with various clinical parameters of the cancer in question." (PMID 37408240, 2023). "VEGFR1 causes an increase in B-cell leukemia/lymphoma-2 (Bcl-2) expression in cancer cells; this protein activates nuclear factor κB (NF-κB), the transcription factor responsible for the increase in CXCL1 expression, as well as CXCL8." (PMID 37408240, 2023). "As a result, CA-MSCs secrete immune cell suppressor molecules and chemokines such as ICAM-I, PD-L1, VCAM, HLA-G, COX-2, IDO, TGF-β, PGE2, CXCL11, CXCL8, CXCL9, CXCL6, CXCL10, CXCL1, and promote cancer cells viability and increase their growth." (PMID 38022534, 2023). "It has also been documented that CXCL1 plays a role in Tregs recruitment and accumulation and promotes angiogenesis in some cancers." (PMID 37059586, 2023). "After 96 h of M0 incubation with cancer cell spheroids, CXCL1 was increased in their culture medium (from M0 0.21 ng/mL to S + M0 0.31 ng/mL, p = 0.0187)." (PMID 37445941, 2023). "Based on individual cancer stages, the median methylation level of CXCL1 in stage 1 was 0.058, in stage 2 was 0.079, in stage 3 was 0.089, and in stage 4 was 0.068." (PMID 36614235, 2023). "The cell types more abundant in LUSC (SOX2, CDKN2A, proliferating cancer) were placed later in pseudotime than the LUAD-specific cell types (alveolar, pathological alveolar, CXCL1 cancer)." (PMID 36973297, 2023). "CXCL1 is known to promote neoplastic transformation, tumorigenesis, and angiogenesis in multiple cancer types by binding CXCR2 (CXCR2 was also increased in our analysis, data not shown)." (PMID 36975480, 2023). "CXCL1 increases cancer cell proliferation and increases glycolytic enzyme expressions, such as glucose transporter 1 (GLUT1), hexokinase 2 (HK2), and lactate dehydrogenase A (LDHA)." (PMID 37408240, 2023). "After the treatment of cisplatin or adriamycin/cyclophosphamide, increased neutrophils were detected in metastatic lungs instead of primary cancer due to the CXCL1/CXCL5 secretion." (PMID 38023616, 2023). "Through recruitment of CD11b+Gr1+ myeloid cells to the TME, Cxcl1 contributes to cancer survival and metastasis." (PMID 36693903, 2023). "The relevance of TAMs in CSC biology is reinforced by a growing list of TAM-derived factors, including IL -6, IL-8, and CXCL1, that have been implicated in the maintenance of CSC stemness in different types of cancer." (PMID 36735677, 2023). "CXCL1 also mediates neutrophil recruitment and activation and, similar to IL-8, was reported to support cancer growth, angiogenesis, and metastasis." (PMID 35739379, 2022). "We grouped CXCL1 gene mRNA expression levels in cancer tissues of COAD patients into groups and calculated the relationship between CXCLI gene mRNA expression and clinical factors of patients." (PMID 35958781, 2022). "The CXC chemokines (e.g., CXCL1, CXCL2, CXCL3, CXCL5, and CXCL8) are significantly upregulated in most cancers and positively associated with cancer metastasis and chemo-resistance." (PMID 36612163, 2022). "For example, overexpression of CXCL1 is involved in primary cancer development and also during metastasis by promoting angiogenesis." (PMID 35159215, 2022). "Comparing the secretion of CXCL1 from 4T1 and E0771 cells, alone or in coculture with BMDMs, revealed significantly lower or unmeasurable CXCL1 levels in the cancer cells alone." (PMID 35998057, 2022).
cancer (continued). "Among these, only CXCL1 secretion was also increased in astrocytes by direct co-culture with cancer cells." (PMID 35411077, 2022). "TNF-α secreted by macrophages promotes the expression of CXCL1, which is involved in cancer development and malignant progression." (PMID 36552865, 2022). "This review describes the role of CXCL1, a chemokine crucial in inflammation as a chemoattractant for neutrophils, in physiology and in selected major non-cancer diseases." (PMID 35457023, 2022). "Due to the contribution of the CCL2/CCR2 and CXCL1/CXCR2 axes to the pathology of various cancers, there have been attempts to develop CCR2 and CXCR2 antagonists, anticipating therapeutic benefits from CCR2 and CXCR2 inhibition." (PMID 36403057, 2022). "Since the first experiments on CXCL1, this chemokine is considered an important factor in cancer development." (PMID 35054978, 2022). "Emerging evidence confirms that chemokines, including chemokine (C-X-C motif) ligand 1 (CXCL1), enhance cell proliferation and invasion in high-grade prostate cancer, gastric cancer, and other cancers." (PMID 34813418, 2022). "The effect of pro-inflammatory cytokines on CXCL1 expression is important because of inflammatory responses in malignant tumors." (PMID 35054978, 2022). "This concentration is more than 100 times higher than the concentration of CXCL1 in normal- and cancer-tissue homogenates." (PMID 35054978, 2022). "A total of 73 genes with pearson correlation coefficient (PCC) ≥ 0.30 were found, in which cancer-associated chemokines CCL20, CXCL8 and CXCL3 were extremely associated with CXCL1 expression." (PMID 35764974, 2022). "The CXCL1 ability to increase proliferation applies mainly to cancer cells, and also, for example, to oligodendrocyte precursors." (PMID 35457023, 2022). "Consistent with our results, several positive feedback loops between cancer cells and TAMs, such as the GM-CSF-CCL18 loop, which promotes metastasis, and the CXCL1/2-S100A8/9 loop, which causes chemoresistance, have been reported." (PMID 35033156, 2022). "Next, we confirmed the effect of macrophages on CXCL1 production in cancer cells using a coculture system." (PMID 36552865, 2022). "The treatment with the TNF-α neutralizing antibody in the CM of WT BMDMs and KLK6-overexpressing RAW 264.7 cells suppressed CXCL1 production from cancer cells." (PMID 36552865, 2022). "To further confirm the effect of PARs on the production of TNF-α in macrophages and CXCL1 in cancer cells, we treated RAW 264.7 cells with a PAR1 or PAR2 inhibitor." (PMID 36552865, 2022). "The following sections discuss the role of CXCL1 in the physiology of selected organs and its role in selected non-cancer diseases." (PMID 35457023, 2022). "CXCL1 is involved in many cellular processes such as inflammation, angiogenesis, and neutrophil recruitment, and its role in cancer has been investigated extensively." (PMID 36078063, 2022). "The results showed that compared with normal cells (N), the NLRP3, EDN1, HMOX1, and CXCL1 genes were upregulated in the cancer cell group (T)." (PMID 36118079, 2022). "On the other hand, patients with early-stage cancer have lower levels of CXCL1 compared to advanced forms of the disease and healthy volunteers." (PMID 36431173, 2022). "CXCL1 can also increase its own expression via NF-κB activation, a mechanism that is important in cancer." (PMID 35054978, 2022). "Chemokines (CCR1, CCR2, CCR3, CCR4, CCR5, CCR6, CCR7, and CCR8) and receptor genes (CXCL1-17, CCL1-14, CCL16-26) were positively associated with necroptosis levels in various cancers." (PMID 36170029, 2022). "Due to a lack of reviews that precisely describe the regulation of CXCL1 expression and function, in this paper, we present the mechanisms of CXCL1 expression regulation with a special focus on cancer." (PMID 35054978, 2022).
cancer (continued). "To determine the effect of TNF-α on macrophage-mediated CXCL1 production in cancer cells, we treated B16F10 cells with the CM of mock-transfected or KLK6-transfected RAW 264.7 cells in the presence or absence of the TNF-α neutralizing antibody." (PMID 36552865, 2022). "Based on the analysis of immune infiltrates across diverse cancer types, abnormal expression of CXCL1 has been found in numerous types of malignancies and has been associated with metastasis, angiogenesis, and chemoresistance." (PMID 33959656, 2021). "Previous studies have revealed that CXCL1 is involved in the signaling axis, immune suppression, and chemoresistance of cancer cells." (PMID 34269159, 2021). "Cancer cells expressed high levels of ligands CXCL1, CXCL2, CXCL3, and CXCL8, signaling to the receptors CXCR1 and CXCR2 expressed by neutrophils." (PMID 33953163, 2021). "We found that cancer stem-like cell cluster LuE2 highly expressed Cxcl1, while the immune cells from cluster 8 defined as macrophages specifically highly expressed the corresponding receptor, Cxcr2." (PMID 34675206, 2021). "On the other hand, Cxcl1- expressing cancer cells stably exhibited an increased migration and invasion abilities." (PMID 34210998, 2021). "The genes (CXCL1, CXCL3, CXCL8, NFKBIB, and SRC) associated with chemokine pathway signaling result in changes in the cellular microenvironment that favor cancer and transformation in L-LVL cells." (PMID 34680563, 2021). "The current study indicates PGG potential as an anti-cancer compound, inhibiting the expression of TNFα-induced CXCL1 via inhibition of the expression of genes and proteins involved in the NFқB and MAPK signaling in MM-231 and MM-468 TNBC cell lines." (PMID 33707603, 2021). "In terms of the immunosuppressive TME, ADQ significantly elevated the infiltration of TILs within the TME and induced cancer cell apoptosis by inhibiting TAM/CXCL1 activity." (PMID 34461944, 2021). "In our study, we found that the cancer stem-like cell cluster LuE2 secreted the specific cytokine Cxcl16 and Cxcl1." (PMID 34675206, 2021). "CXCR2, receptor of CXCL1, is highly expressed on the surface of neutrophils and is involved in progression in several kinds of cancer, such as lung, prostate, breast, colorectal, ovarian, and pancreatic cancer." (PMID 34760697, 2021). "Collectively, our data suggested CXCL1 up-regulation as a novel potential diagnostic biomarker in CRC patients of different races, cancer stages, genders, age groups, and body weights." (PMID 34473751, 2021). "CXCL1 is expressed in a wide range of human cancers which makes it a potential therapeutic target to inhibit invasion and metastasis." (PMID 33126568, 2020). "These cells were recruited to tumors by cancer cell-derived CXCL1/2 chemokines, and served as a major source for the pro-inflammatory proteins S100A8 and S100A9." (PMID 33585241, 2020). "When CXCL1 neutralizing antibody was added to the co-culture system, the proliferation promoting effects were inhibited, indicating CXCL1 is a critical chemokine in TAMs-CM activating HSPCs-mediated cancer cell proliferation." (PMID 32213179, 2020). "Network pharmacology analysis combined with experimental validation discovered that XIAOPI formula plays the anti-cancer effects mainly via inhibiting the TAMs/CXCL1 pathway." (PMID 32213179, 2020). "Induce secretion of proinflammatory cytokines (CXCL-1,−2,−3 and IL-8) in stromal cells and facilitate cancer progression." (PMID 32754615, 2020). "S100A8/9 and CXCL1/2, or S100A7/8/9 and IRAK1, form a feedback loop to cause cancer chemoresistance and drive breast cancer tumor sphere growth." (PMID 32547883, 2020).